SCARB1 (scavenger receptor class B member 1)
Diseases named in the same sentence as SCARB1 in open-access papers (continued):
Sharing a sentence is not in itself a finding about the gene and the disease.
tumor (112 papers, 2010 to 2026). "Whether the observed tumor immunity in our present study is associated with these previously reported phenotypic changes in immune cells of Scarb1-null mice is unknown." (PMID 29069761, 2017). "We further demonstrate that SCARB1-mediated cholesterol uptake is essential for the activation of mTORC1, which promotes tumour growth by preventing excessive autophagy in HCC cells." (PMID 42265306, 2026). "SCARB1 promotes reprogramming of lipid metabolism in tumor cells by mediating high-density lipoprotein (HDL) uptake." (PMID 40649911, 2025). "BLT-1 currently resides in early-phase clinical development with demonstrated preclinical efficacy in disrupting APOE/SCARB1-mediated tumor progression pathways." (PMID 41390817, 2025). "Through IHC, the protein expression of SCARB1 was detected on tumor cells, which was consistent with previous bioinformatics data." (PMID 37801479, 2023). "SKCM patients with advanced tumor state (pathologic T stage 3–4, Clark level IV-V, and Breslow depth >3 mm) tended to express more abundant SCARB1 significantly (all p < 0.05)." (PMID 37801479, 2023). "rs4765623/SCARB1 exhibited tumor-specific enhancer activity and was validated in a 786-O cell line, with the C risk allele enriched for chromatin activity, consistent with its expression increasing effect in our study." (PMID 35804456, 2022). "In Univariate and Multivariate analysis, traditional clinicopathological features (including tumor size, Grade and TNM stage), SCARB1 were associated with DFS." (PMID 33912215, 2021). "The scavenger receptor class B type 1 (SR-BI, gene name SCARB1) has emerged as a novel tumor marker, since its expression in different types of tumor cells has been associated with progression of the disease." (PMID 30823658, 2019). "In this context, SCARB1, which has been involved in tumor development, tended to be downregulated when compared the most aggressive tumors with BTT group, although these changes were not significantly different." (PMID 31311983, 2019). "Expression of SCARB1 drives tumour growth in a number of different cancers including breast and prostate cancer." (PMID 29352211, 2018). "Global knockout of Scarb1 (SR-B1) in 2-3 month old tumor bearing animals on chow diet led to inhibition of B16F10 tumor development compared to WT animals and increased levels of circulating HDLc." (PMID 29069761, 2017). "The same variant was also a marginal eQTL for SCARB1 but is not an eQTL in the normal, strongly supporting its tumor-specific effect." (PMID 35804456, 2022). "This suggests that in our tumor-bearing animals the increased total plasma cholesterol in SR-B1 null mice relative to Scarb1+/−, may have primarily partitioned to LDL instead of HDL particles." (PMID 29069761, 2017). "Furthermore, genes previously associated with ccRCC susceptibility or carcinogenesis, apolipoprotein C-I (APOC1), vascular endothelial growth factor A (VEGFA), scavenger receptor class B, member 1 (SCARB1) were found to be highly overexpressed in tumour tissue in both analysis." (PMID 23526956, 2013). "To investigate the efficacy of co-treatment with the SCARB1 inhibitor BLT-1 and TMZ on tumor recurrence after TMZ treatment, we used PDC, PDO, and PDX from the same patient." (PMID 41390817, 2025). "The interruption of APOE-mediated lipid uptake via a SCARB1 inhibitor named as block lipid transport-1 (BLT-1), suppressed TMZ-induced HRR activation and sensitized tumor cells to TMZ treatment in preclinical models, including PDCs, PDOs, and PDXs." (PMID 41390817, 2025). "In our study, we demonstrated that TMZ stimulates tumor cells to secrete APOE, which then interacts with increased SCARB1 to initiate a series of cascade reactions." (PMID 41390817, 2025).
tumor (continued). "Tumours that rely upon cholesterol and HDL signalling and which express the HDL receptor SCARB1, may be particularly sensitive to these nanoparticles." (PMID 29352211, 2018). "In contrast, however, tumor growth in Scarb1+/− mice was significantly (p<0.05) inhibited by approximately 3-fold relative to WT mice, with no significant further reduction in growth of tumor observed in Scarb1−/− mice." (PMID 29069761, 2017).
cancer (78 papers, 2013 to 2025). A tumor composed of atypical neoplastic, often pleomorphic cells that invade other tissues. "This correlates with the expression of genes in cancer patients, where cholesterol uptake genes such as SCARB1 are overexpressed and, in contrast, genes implicated in cholesterol anabolism are downregulated." (PMID 38893271, 2024). "In fact, their associations (SCARB1 most in all investigated 33 cancers, followed by NRP1 in 31 cancers, TMPRSS2 in 27 cancers, AXL in 25 cancers and ACE2 in 13 cancers) appeared in more cancer types than those of CNVs with the same trends among the five STGs." (PMID 36875081, 2023). "Overexpression of SCARB1 has been associated with cancer development and shown to be inversely correlated with survival in multiple cancer types, although no molecular mechanism was proposed." (PMID 33097743, 2020). "The SCARB1 gene encodes a protein that may be a potential target in various human cancers, including HCC." (PMID 39453509, 2024). "Mounting studies have reported the significant role of SCARB1 gene and SR-BI protein in cancer proliferation and progression." (PMID 40313394, 2025). "Cancer cells can also acquire extracellular cholesterol, especially HDL-cholesterol, via scavenger receptor class B type 1 (SR-B1 that is encoded by SCARB1 gene)." (PMID 37420029, 2023). "SCARB1 has been demonstrated to be involved in cholesterol metabolism, thereby facilitating cancer progression." (PMID 35938006, 2022). "Targeting SCARB1 expressing cells with HDL NPs represents a promising strategy to treat a number of different cancer types that rely upon HDL signalling." (PMID 29352211, 2018). "Furthermore, SCARB1 was highly expressed in cancer tissues and the positive expression rate increased with the degrade of differentiation." (PMID 33912215, 2021). "Here, we show that PS can activate SCARB1 in three cancer types, although more work is needed to determine whether these are driving events." (PMID 33097743, 2020). "TMPRSS2 and AXL was down-regulated often in cancers but SCARB1 showed the reverse trends, while all of three was shown to be expressed abnormally more frequently than ACE2 and NRP1, which could not provide an expression patten possibly due to their limited situations." (PMID 36875081, 2023). "MAP3K1 encodes a MEK kinase involved in the regulation of cell proliferation, SCARB1 plays an important role in the regulation of cell homeostasis by maintaining the level of cholesterol available in fibroblasts for androgen synthesis, and S100A10 controls migration of cancer-associated macrophages." (PMID 35740605, 2022). "Although no data on the role of these miRNAs in the context of SCARB1 and cancer is available, recent studies have shown that levels of miR-125a, miR-455, miR-185, and miR-192 are down-regulated in several types of cancer." (PMID 27774064, 2016). "However, the expression of the HDL-receptor, SCARB1, in SHH-driven cancers has not been studied." (PMID 29352211, 2018).
infection (75 papers, 2009 to 2026). The state of being infected such as from the introduction of a foreign agent such as serum, vaccine, antigenic substance or organism. "This study reports the role of SCARB1 in infection and its potential association in TLR4 signaling on bacterial challenge in Goat mammary epithelial cells (GMECs)." (PMID 36604713, 2023). "Overall, it indicates that coliform mastitis triggers SCARB1 expression in vivo and this receptor is involved in infection in dairy goats." (PMID 36604713, 2023). "In order to understand the role of SCARB1 during in vitro E.coli induced infection, the GMECs were stimulated at multiple time points and MOIs in this study." (PMID 36604713, 2023). "The role of SCARB1 in the entry of E. coli in MECs during infection is significant as bacterial intramammary infections in cattle as well as in humans are a major concern." (PMID 36604713, 2023). "Also, at 24 h post-infection, SCARB1 mRNA and protein expression was significantly decreased on increasing MOIs, which is consistent with our RNA Seq data." (PMID 36604713, 2023). "Later, other receptors and entry cofactors of SARS‐CoV‐2 were uncovered, including AXL, NRP1, SCARB1 etc.,27, 28, 29 which may explain its infection in tissues with low ACE2 expression." (PMID 35917402, 2022). "Four cell-surface molecules, CD81, occludin (OCLN), claudin 1 (CLDN1), and scavenger receptor class B member 1 (SRB1), are particularly important for HCV cell entry, although only CD81 and OCLN determine the species-specificity of infection." (PMID 29765366, 2018). "So, the focus was on the association of SCARB1 receptor with TLR4 signalling pathways in infection in dairy ruminants, which has not been highlighted earlier as most studies have focused on the role of SCARB1 as a lipoprotein receptor." (PMID 36604713, 2023). "No significant changes in SCARB1 mRNA and protein expression were notable between the non-infected control and hk E.coli group at 3 h post-infection (1.176–1.226 folds, P < 0.05)." (PMID 36604713, 2023). "Similarly, SCARB1 protein levels were significantly decreased on infection with hk E.coli after 24 h as compared to the non-infected control group." (PMID 36604713, 2023). "However, cells challenged for 3 h with the same infection points showed no significant change in SCARB1 mRNA and protein expression." (PMID 36604713, 2023). "While rodent malaria parasite infection may be limited by naturally occurring SR-B1, this is different for Pf as there is an upregulation of SCARB1 transcripts after infection which can be either a host response to infection or active parasite manipulation of host." (PMID 37532704, 2023). "Similarly, on infection with hk E.coli at 1:100, 1:300 and 1:500 MOIs after 6 h, protein levels of SCARB1 were significantly increased as compared to a non-infected control group with an increase in MOI (P < 0.05, P < 0.01)." (PMID 36604713, 2023).
cardiovascular disease (20 papers, 2010 to 2025). "Several studies have reported that loss of SCARB1 function is associated with increased cardiovascular disease risk." (PMID 39448372, 2025). "Significant sex-dependent associations between SCARB1 genetic variations with lipid profile, BMI, and risk of cardiovascular disease have been previously shown." (PMID 26754576, 2016). "Furthermore, recent genomic analyses have shown that SR-B1 has a protective effect against AS in humans, as carriers of SCARB1 variants with associated SR-B1 dysfunction were shown to be at an increased risk of cardiovascular disease." (PMID 35087605, 2022). "While in human, previous studies have identified that humans who carry mutations in a SCARB1 gene (a gene encoding human SR-BI), exhibited relatively higher plasma HDL-C levels and increased risk of cardiovascular disease." (PMID 30144814, 2018). "We previously reported association of SCARB1 SNP rs10846744 with common carotid IMT (cIMT) and cardiovascular disease (CVD) events." (PMID 30289950, 2018).
metabolic disease (5 papers, 2018 to 2025). A congenital disorder (due to inherited enzyme abnormality) or acquired (due to failure of a metabolically important organ) disorder resulting from an abnormal metabolic process. "SCARB1 and SOAT1, despite evidence from metabolic disease models indicating that modulation of transcytosis or cholesterol esterification can alter intracellular lipid handling, currently lack any marketed therapeutics." (PMID 41446579, 2025).
GI tumor (2 papers, 2022 to 2024). "We therefore characterized the expression profiles of a number of genes involved in SARS-CoV-2 infection pathway and found higher ACE2, TMPRSS2, TMPRSS4, SCARB1, CTSL and NRP1 expression in all GI tumor samples relative to their normal counterparts." (PMID 35970857, 2022).
heart disease (1 paper, 2024).
SCARB1 also shares sentences with these, for which no sentence is quoted: hyperlipidemia (8 papers); COVID-19 (7); lung carcinoma (6); ovarian carcinoma (6); colorectal cancer (5); endotoxemia (5); Hypertension (5); type 2 diabetes (5); fibrosis (4); Hyperglycemia (4); leukemia (4); steatosis (4); Stroke (4); tuberculosis (4); Alzheimer disease (3); autoimmune (3); endothelial dysfunction (3); gallstones (3); lipid metabolism disorder (3); liver dysfunction (3); prostate tumor (3); acute myocardial infarction (2); adenoma (2); age-related macular degeneration (2); aortic atherosclerosis (2); bacterial infection (2); cardiac hypertrophy (2); Cerebral ischemia (2); chronic renal failure (2); coronary stenosis (2).
A further 97 diseases each share a sentence with SCARB1 in 2 papers or fewer.